LUCAT1 (lung cancer associated transcript 1)
Diseases named in the same sentence as LUCAT1 in open-access papers (continued):
Sharing a sentence is not in itself a finding about the gene and the disease.
cancer (68 papers, 2014 to 2026). A tumor composed of atypical neoplastic, often pleomorphic cells that invade other tissues. "Despite this, the underlying mechanism of LUCAT1 contributing to cancer the occurrence and progression, particularly in chemoresistance of BC, remains elusive." (PMID 40025525, 2025). "Gene set enrichment analysis (GSEA) further indicated the involvement of LUCAT1 in cancer hallmark pathways, such as APICAL_JUNCTION, COMPLEMENT, and TNFA_SIGNALING_VIA_NFKB." (PMID 39594666, 2024). "Some of the target genes in the LUCAT1 ceRNA network have been known to associate with the elevated migratory potential of cancer cells, and hence we queried the impact of LUCAT1 silencing on the migratory potential of TNBC cells." (PMID 39594666, 2024). "LUCAT1, which is also known as smoke and cancer-associated lncRNA1, is highly expressed in various malignancies." (PMID 37259023, 2023). "LUCAT1 (lung cancer-associated transcript 1) lncRNA is shown to be overexpressed in several cancer types including smoking-related LC." (PMID 38203731, 2023). "Lung-cancer-associated transcript 1 (LUCAT1) is an lncRNA known to regulate growth and metastasis in various cancer types." (PMID 36769116, 2023). "It has been reported that upregulation of lncRNAs in lung cancer are associated transcript 1 (LUCAT1) which enhances cancer proliferation via EZH2 overexpression." (PMID 35236381, 2022). "This study aimed to characterize the role of lncRNA lung cancer‐associated transcript 1 (lncRNA LUCAT1), a novel cancer‐related lncRNA, in human PDAC." (PMID 31789465, 2020). "The smoke- and cancer-associated lncRNA 1 (SCAL1 or LUCAT1) is a cancer lncRNA related to smoke exposure that is strictly associated with NRF2 activity." (PMID 33287295, 2020). "Compared with other studies, our study showed a causal role of LUCAT1 in cancer via the CRISPR/Cas9 system for the first time." (PMID 33097685, 2020). "Although there are substantial studies revealing that lung cancer-associated transcript 1 (LUCAT1) functions as a tumor promotor in various human cancers, the molecular mechanism of LUCAT1 in TNBC remains largely to be explored." (PMID 31399501, 2019). "A subset of our relapse-specific lncRNAs (n = 61) overlaps with the prognostic markers identified from 14 Pan-Cancer datasets, including lung cancer-associated transcript 1 (LUCAT1), which is previously reported for its drug resistance in solid cancer." (PMID 30642353, 2019). "Previous researches have substantial evidence that lncRNA lung cancer-associated transcript 1 (LUCAT1) is recognized as a tumor promoting gene in a wide range of human cancers." (PMID 31399501, 2019). "In this study, after a previous screening of several lncRNAs on PTC tissues, we focused on “lung cancer associated transcript 1” (LUCAT1)." (PMID 31591432, 2019). "Recently, several studies have indicated that lung cancer associated transcript 1 (LUCAT1) is a cancer-related and myeloid cell-specific lncRNA that can interact with signal transducer and activator of transcription 1 (STAT1) to inhibit the transcription of interferon-stimulated genes." (PMID 40833782, 2025). "Notably, LUCAT1, a well-studied lncRNA, has been linked to chemotherapy resistance across several cancer types." (PMID 41145422, 2025). "Lung-cancer-associated transcript 1 (LUCAT1) has been identified in several human cancers, but its role in HCC is unknown." (PMID 36901717, 2023). "lncRNA lung cancer associated transcript 1 (LUCAT1) has been widely reported in diverse cancers." (PMID 35711895, 2022). "Importantly, LUCAT1 was shown to be associated with tumorigenesis and poor prognosis of cancer patients and participated in chemoresistance." (PMID 32998707, 2020). "Finally, different associations of LUCAT1 with other types of cancers have been also published, such as in glioma, where it regulates miR-37526 and in osteosarcoma, where it acts through miR-200c/ABCB1 pathway." (PMID 31591432, 2019).
cancer (continued). "LUCAT1 (Lung Cancer Associated 1) is located at chromosome 5q14.3." (PMID 30416681, 2018). "This study demonstrates that knockdown of the long non-coding RNA (lncRNA) LUCAT1 markedly reduces cancer cell stemness." (PMID 42318476, 2026). "Previous studies have highlighted a significant correlation between LUCAT1 and the malignant progression of various cancers." (PMID 41145422, 2025). "Our search for LUCAT1 reveals that it is predominantly expressed in myeloid cells in most cancers including lung cancer and colorectal cancer, and is also highly expressed in myeloid cells in normal tissues including lung and esophagus tissues." (PMID 40833782, 2025). "Mechanistically, our comprehensive transcriptional analysis revealed that LUCAT1 significantly upregulates HMGA1 expression, a key regulatory gene associated with cancer stem cell properties." (PMID 40025525, 2025). "Accumulating evidence has demonstrated that lung-cancer-associated transcript 1 (LUCAT1), also known as smoke-and-cancer-associated lncRNA 1 (SCL1), is involved in the progression of multiple types of cancer." (PMID 38540273, 2024). "Through the virtue of modulating the anti-cancer miRNA-oncogenic mRNA, LUCAT1 can act as a stimulator of cancer growth." (PMID 39594666, 2024). "Decreased expression of stemness-associated genes upon LUCAT1 modulation prompted us to evaluate the impact of LUCAT1 silencing on the expression level of the stemness marker CD49f and identify the population of cancer stem cells/progenitor cells in TNBC." (PMID 39594666, 2024). "Initially identified in lung cancer, LUCAT1 has been found to regulate tumor progression in other cancer types as well." (PMID 38711918, 2024). "LUCAT1, UCA1, and MIR31HG were significantly increased in the cancer group (p < 0.05), particularly LUCAT1 and MIR31HG (p < 0.0001)." (PMID 36980216, 2023). "In this study, many lncRNAs in the risk model, such as ZFPM2-AS1, NRAV, LUCAT1, MKLN1-AS, and LINC01224, were found to exert vital roles in regulating and participating in the progression of different cancers." (PMID 35712653, 2022). "On the basis of a literature review, LUCAT1 has been found to play an oncogenic role in diverse cancers, including TNBC." (PMID 35711895, 2022). "Previous studies have demonstrated that the expressions of SNHG17, RUSC1-AS1, LINC02609, and LUCAT1 were significantly increased in many cancers." (PMID 35118117, 2021). "Among the lncRNAs expressed in OS-R only, LUCAT1 was found to modulate cancer cell viability and chemotherapy response in various cancer types, including lung, thyroid and CRC." (PMID 35201486, 2021). "Among the five ferroptosis-related lncRNAs in the model, LUCAT1 has been confirmed to be effective in promoting the progressions of various cancers." (PMID 34745200, 2021). "Previous studies demonstrated that aberrant expression of LUCAT1 is correlated with several cancers." (PMID 34736453, 2021). "All of these studies indicate that LUCAT1 is closely correlated with the development of various cancers." (PMID 34736453, 2021). "LncRNA LUCAT1 is recently characterized as a tumor-promoting lncRNA in a wide variety of cancers, including osteosarcoma, non-small cell lung cancer, esophageal cancer, and renal cell carcinoma." (PMID 32998707, 2020). "Like other lncRNAs, LUCAT1 has been proven to participate in carcinogenesis and cancer progression by regulating gene expression through a posttranscriptional mechanism." (PMID 33097685, 2020). "LUCAT1 are found to share conserved binding site with these miRNAs and then modulates cancer progression through their direct interaction." (PMID 33097685, 2020). "Previous reports demonstrated that LUCAT1 is often upregulated in several types of cancer cells and promotes the proliferation, invasion or migration of these cells from many cancer types including CRC." (PMID 31964396, 2020).
cancer (continued). "The results showed that LUCAT1 expression in cancer tissues was higher than that in adjacent normal tissues in CRC patients (p = 0.024)." (PMID 33097685, 2020). "Among these lncRNAs, LUCAT1 influences the proliferation, migration, and invasion of tumor cells, being involved in the cell cycle of many cancer cells." (PMID 33102579, 2020). "Consistently, immunohistochemical (IHC) staining showed a lower Ki67 expression in LUCAT1-KO tumor tissue compared to NC group, suggesting a hindered proliferative ability of LUCAT1-KO cancer cells." (PMID 33097685, 2020). "We detected LUCAT1 expression in 26 pairs of fresh specimens by qRT-PCR and found LUCAT1 expression in cancer tissues was higher than matched adjacent normal tissues (p < 0.01)." (PMID 31300015, 2019). "Mounting evidence has corroborated that LUCAT1 exerts its oncogenic function in a variety of cancers." (PMID 31399501, 2019). "LUCAT1 has been found to be implicated in different biological processes in a broad variety of cancers, which reinforces its potential oncogenic role, but, to our knowledge, this is the first study analysing LUCAT1 and its role in PTC development." (PMID 31591432, 2019). "Our results proofed that LUCAT1 functioned as a cancer promotor by affecting cell proliferation, cycle, apoptosis, and metastasis of TNBC." (PMID 31399501, 2019). "Our clinical investigations revealed CTD-2357A8.3 (SCAT1) and LUCAT1 (SCAT5) as common independent prognostic biomarkers for lung and kidney-derived cancers, respectively." (PMID 29491376, 2018). "Mechanistically, LUCAT1 could significantly up-regulate HMGA1 expression, a key regulatory genes of cancer stem cell, and inhibition of malignant phenotypes in BC cells by silencing LUCAT1 was reversed by overexpression of HMGA1." (PMID 40025525, 2025). "Recently, accumulating research indicates that LUCAT1 plays a favorable role in post-transcriptional regulation of multiple key oncogenes, and dysregulated expression of LUCAT1 has been connected to cancer stem cells (CSCs)." (PMID 40025525, 2025). "LUCAT1 also impacts several signal transduction pathways in multiple cancer types." (PMID 39594666, 2024). "A more comprehensive understanding of LUCAT1’s role in tumorigenesis may pave the way for developing novel cancer treatment strategies." (PMID 38711918, 2024). "Since LUCAT1 can distinguish between normal and cancer groups with high efficacy, it may serve as an excellent diagnostic biomarker for HNC." (PMID 36980216, 2023). "LUCAT1 exhibits high expression in various types of cancers." (PMID 37945918, 2023). "Silencing LUCAT1 remarkably diminishes cancer progression and malignancy." (PMID 35236381, 2022). "Accumulative evidences have shown that LUCAT1 is involved in the progression of several cancers." (PMID 35118117, 2021). "In this study, we found that LUCAT1 upregulation in CRC leads to cancer cell proliferation." (PMID 33097685, 2020). "Moreover, the role of LUCAT1 has been reported to be active mainly in cancer cells, particularly, with regard to its involvement in the regulation of cancer cell migration and invasion." (PMID 33426083, 2020). "LncRNA LUCAT1 is a potential tumor promoter in human cancers." (PMID 32998707, 2020). "LUCAT1 is widely considered as an oncogene in various cancers." (PMID 31968402, 2020). "Given that EMT can enhance the migration and invasion capabilities of cancer cells, we speculated that LUCAT1 may be involved in the EMT." (PMID 33426083, 2020). "The downregulation of EZH2 observed in our cell lines, could be produced by the reduced expression of CDK1 after LUCAT1 knockdown that thus promotes the aberrant cell transformation to cancer cells." (PMID 31591432, 2019).
cancer (continued). "LUCAT1 and other potential specific therapeutic targets may suppress malignant tumor by inhibiting BCSCs stem phenotype conversion." (PMID 31300015, 2019). "Emerging studies have proven that LUCAT1 is an oncogene in human cancer." (PMID 31399501, 2019). "Furthermore, after the overexpression of LUCAT1, most biological Metabolic pathways, including Glycerolipid metabolism and cancer-related pathways such as the Chemical carcinogenesis−receptor activity pathway, increased significantly, which also proved the role of LUCAT1 in promoting cancer." (PMID 36401283, 2022). "LUCAT1 could promote tumorigenesis and development in various cancers." (PMID 34663322, 2021). "As expected, we finally identified 26 prognostic cancer-related lncRNAs and constructed a prognostic risk model with ten lncRNAs (including RP11-573D15.8, LINC01317, RNF144A-AS1, TFAP2A-AS1, LINC00702, GAS6-AS1, RP11-400K9.4, LUCAT1, RP11-63A11.1, RP11-156L14.1)." (PMID 34663322, 2021). "In addition, LUCAT1 upregulation was also reported in other cancer types." (PMID 33097685, 2020). "Moreover, the expression level of LUCAT1 was detected in 4 human CRC cell lines (HCT116, HT-29, SW620, and SW480) and normal human colonic epithelial NCM460 cells, and the results showed that LUCAT1 was significantly higher in cancer cell lines than in NCM460 cells." (PMID 33097685, 2020). "Yoon and colleagues demonstrated that LUCAT1 expression is also increased in ESCC cell lines and cancer tissues." (PMID 38540273, 2024). "LncRNAs, such as HOTAIR, H19, LncTCF7, LUCAT1, MALAT1, LINC00511, and FMR1-AS1, have been described as key regulators of stemness in cancer, allowing cancer cells to acquire this phenotype." (PMID 35954194, 2022). "LncRNAs, such as LUCAT1, KCNMB2-AS1, CASC15, MIAT, PTOV1-AS2, LINC00680, and RNF217-AS1 were reported to be up-regulated in ESCC and other malignant tumors, validating our RNA-sequencing results." (PMID 35255921, 2022). "The presence of LUCAT1 allows the transcription factor mRNA to be translated into protein which activates the WNT signaling pathway, resulting in cancer cells with stem characteristics." (PMID 35954194, 2022). "MiR-5702 was found to possibly bind with LUCAT1 by LncBase Predicted v.2 database and the expression of miR-5702 was remarkably reduced in TNBC tissues in comparison to non-cancer tissues." (PMID 31399501, 2019). "Collectively, these findings show that LUCAT1 constitutes a key regulatory component within the cancer stemness regulatory network of HNSCC, and underscores the function of the LUCAT1/miR-128 axis in sustaining stem cell-like traits and driving HNSCC malignant progression." (PMID 42318476, 2026). "Furthermore, IGF2BP2 expression positively correlated with LUCAT1, HMGA1 and cancer stem cell markers expression in BC cells." (PMID 40025525, 2025). "In our study, qRT-PCR analysis of human samples revealed that while the difference in LUCAT1 expression between cancer and adjacent tissues was not pronounced, tumor tissues exhibited higher LUCAT1 expression compared to normal liver tissues." (PMID 37945918, 2023). "Furthermore, several cancer-promoting or tumor-suppressing lncRNAs, such as NEAT1, H19, NRON, LUCAT1, and HOTAIR, can be found not only in malignant cells but also in tumor-specific immune cells." (PMID 36911393, 2023). "Previous evidences outlined the exosome-mediated secretion of lncRNAs and their detection in serum of cancer patients, thus we tested HCC derived cell lines for CASC9 and LUCAT1 expression in the intra and extracellular compartment, as well as in the exosomal fraction of cell culture supernatant." (PMID 30416681, 2018). "The expression of PVT1 and LUCAT1 was significantly increased, and the expression of LINC00982 was significantly decreased in tumor patients, which is in line with available publications analyzing the significance of these lncRNAs not only in RCC but also in other cancers." (PMID 35441392, 2022).
cancer (continued). "Further, we established the prognostic model of six HRlncRNAs (LUCAT1, MIR4435-2HG, LINC01711, AP000695.2, ADAMTS9-AS2, and AC087521.1) by means of univariate and multivariate cox and lasso regression analyses to explore the potential influence in pan-cancer of the digestive system." (PMID 35574385, 2022). "Specifically, in obese subjects we found several lncRNAs (e.g., ZFAS1, LUCAT1, HIF1A-AS1, HOXB-AS3) already identified in the setting of different type of cancers, but not previously reported in human AT." (PMID 32714872, 2020).